MUC2 (mucin 2, oligomeric mucus/gel-forming)
Diseases named in the same sentence as MUC2 in open-access papers (continued):
Sharing a sentence is not in itself a finding about the gene and the disease.
Stroke (4 papers, 2019 to 2023). Sudden impairment of blood flow to a part of the brain due to occlusion or rupture of an artery to the brain. "Most importantly, this appears to be mediated by E2, as estrogen supplementation in aged female mice prior to stroke led to enhanced expression of Muc2 and Muc4 in the gut epithelium, similar to that seen in ovary-intact females." (PMID 37910478, 2023). "Cromolyn treatment significantly increased the mucus MUC2-producing goblet cells in the intestine 3 days after stroke compared to vehicle-treated stroke mice." (PMID 37805585, 2023). "Along with the reduced MCs seen after cromolyn treatment, we also found significantly increased (P < 0.0001) mucus 2 (MUC2) positive goblet cells in cromolyn-treated mice compared to vehicle-treated stroke mice at 3 days after stroke." (PMID 37805585, 2023). "However, in young female mice, there was a significant increase in mucin genes after stroke (P = .0234 for Muc2 and P = .0434 for Muc4)." (PMID 37910478, 2023). "Our results show reduced goblet cells with MUC2 in stroke animals compared to sham mice." (PMID 37805585, 2023). "Interestingly, E2-replaced stroke mice showed higher expression of Muc2 (P = .0156) and Muc4 (P = .0003), compared with the vehicle-treated group." (PMID 37910478, 2023). "In this study, we observed a small but significant elevation of LPS as well as a 2-fold elevation of muc-2 in sham males as compared to sham females, suggesting that there might be a pre-existing gut leakiness in males that might serve as a substrate for poor stroke outcomes in this sex." (PMID 33451354, 2021). "Two other markers of gut permeability, LPS and Muc-2, were elevated in males irrespective of stroke." (PMID 33451354, 2021). "Interestingly, gene expression of key components that form the mucus layer, mucin 2 (Muc2), mucin 4 (Muc4) and mucin 13 (Muc13) was decreased only in the older mice, but not in young mice, after stroke." (PMID 31199577, 2019).
ulcer (4 papers, 2010 to 2022). "Therefore, the comparison Muc0-1 vs. Muc2 provided the opportunity for better understanding oral microbiome shifts associated with the ‘threshold’ of presence of ulcers in oral cavity." (PMID 32537095, 2020). "In contrast, large invasive ΔespF C. rodentiumStr microcolonies (EUB338+GAM42a+, yellow) could be seen associated with the ulcers in the colons of infected strep-treated Muc2−/− mice." (PMID 20485566, 2010). "While the mechanisms are unclear, we suggest the accumulation of bacteria and microcolony formation on the epithelial surface in a Muc2-deficient environment is linked to either the development and/or maintenance of the ulceration, since most ulcers were associated with the microcolonies." (PMID 20485566, 2010). "Thus the propensity to accumulate bacteria on the surface of a Muc2-deficient mucosa is likely a key contributory factor to the ulcer development that occurs in these mice during infection." (PMID 20485566, 2010). "In humans, expression of MUC2 is reduced or depleted in ileal mucosa close to the ulcer margins in CD, and MUC2 production is also reduced in active UC." (PMID 35732858, 2022). "As a decrease in luminal mucin content may reflect a differential expression of mucin genes, we determine whether the expression of secretory (Muc2) and membrane bound (Muc3) mucin were also altered during the onset of ulcer formation." (PMID 21949848, 2011).
appendix cancer (3 papers, 2020 to 2023). "We confirmed the MUC2 protein‐suppressive effect of dual drug therapy in explant tissue from KRAS mutated mucinous colon/appendix cancers, demonstrating reduced MUC2 protein and mRNA expression levels at 24 hours." (PMID 31958897, 2020). "The overall inhibitory effects of drug therapy on mucin/MUC2 production was confirmed in colonoid cultures from KRAS mutated colon/appendix cancers." (PMID 31958897, 2020). "We investigated the efficacy of dual MEK‐PI3K drug therapy against KRAS mutated mucin 2 (MUC2)‐secreting LS174T cells and patient‐derived ex vivo and in vivo models of KRAS mutated mucinous colon/appendix cancers." (PMID 31958897, 2020). "A unique aspect of mucinous colon/appendix cancers is the abundant production and secretion of MUC2 protein." (PMID 31958897, 2020).
bladder cancer (3 papers, 2013 to 2025). "In the case of bladder cancer, the presence of MUC2 has been associated with the non-invasive proliferation of tumors or with a favorable outcome for patients." (PMID 36674608, 2023).
coccidiosis (3 papers, 2013 to 2023). A parasitic infection caused by Coccidia. "Moreover, our previous study also showed that the mucin (MUC-2) gene expression, which is a key encoded secretory protein for gut barrier protection, was downregulated when chickens were infected with coccidiosis." (PMID 37174598, 2023). "A downregulation in mRNA expression of FABP2 occurred in compromised gut barrier chickens (challenged with coccidiosis vaccine) along with decreased MUC2 and occludin expression, which may indicate an association between FABP2 and gut integrity in chickens." (PMID 34671361, 2021).
diarrhoea (3 papers, 2018 to 2025). "MUC2 not only is vital for maintaining mucosal integrity in the context of weaning-induced diarrhoea but also has been associated with other stress-related conditions, such as necrotising enterocolitis and heat stress." (PMID 39859316, 2025). "It is possible that the increased expression of CLDN3 reduced the translocation of bacteria across the intestinal barrier, while the increased expression of MUC2 reduced the adherence of bacteria to the intestinal cells, thereby reducing the risk of pigs to infection and diarrhoea." (PMID 36258027, 2022). "Compared with those in the unweaned and weaned healthy groups, the MUC2 mRNA and protein levels in the Min pig diarrhoea group were lower, whereas those in the Landrace diarrhoea group were greater than those in both healthy groups." (PMID 39859316, 2025). "Jejunal MUC2 protein expression in the unweaned Min pig group was significantly greater than that in the healthy weaned Min pig group and diarrhoea group (p < 0.05)." (PMID 39859316, 2025). "Across the weaned diarrhoea groups, jejunal and duodenal MUC2 protein expression in the Min pigs was lower than that in the Landrace pigs, whereas the Min pigs presented higher MUC2 protein expression in the other intestinal segments, with a significant difference in the colon (p < 0.01)." (PMID 39859316, 2025). "Since the jejunum is the longest segment of the small intestine, these divergent changes in jejunal MUC2 expression between Min pigs and Landrace pigs may be more closely related to weaning diarrhoea." (PMID 39859316, 2025). "Colonic MUC2 protein expression was lower in the healthy weaned groups of each breed than in the unweaned groups, whereas MUC2 protein expression was increased in the diarrhoea groups." (PMID 39859316, 2025). "MUC2 mRNA expression in the jejuna of Min pigs in the postweaned healthy group was significantly greater than that in the unweaned group (p < 0.05), whereas MUC2 mRNA expression in the diarrhoea group was significantly lower than that in the postweaned healthy group (p < 0.01)." (PMID 39859316, 2025). "To explore the relationship between intestinal mucin 2 (MUC2) and weaning-induced diarrhoea in piglets, we analysed Min and Landrace piglets." (PMID 39859316, 2025). "Although the Landrace diarrhoea group presented greater goblet cell numbers and volumes than the Min pig group did, acute MUC2 secretion did not significantly improve their defence ability, as Min pigs presented lower diarrhoea rates and indices." (PMID 39859316, 2025).
esophageal cancer (3 papers, 2008 to 2022). A primary or metastatic malignant neoplasm involving the esophagus. "We examined the effect of aspirin, a potential chemopreventive agent in the prevention or treatment of esophageal cancer, on expression of MUC2 induced by DCA." (PMID 19014523, 2008). "In esophageal cancer cells, ASA reduces COX-2 expression and inhibits NF-κB nuclear migration, which mediates MUC2 overexpression." (PMID 36676718, 2022).
Giardia infection (3 papers, 2022 to 2024). "Consistent with the protective roles played by mucins during giardiasis, mice deficient for mucin 2 gene (Muc2-/-) showed significantly higher trophozoite burdens in the small intestine and had impaired weight gain as compared with control animals." (PMID 35250996, 2022). "Muc2 is the main gel-forming mucin in the intestinal region, and it has been shown to play an important role during Giardia infections." (PMID 35573800, 2022). "It is also possible that Muc2 crosslinking is altered upon Giardia infection, which may contribute to mucus barrier thinning." (PMID 39412866, 2024).
Hepatic steatosis (3 papers, 2016 to 2025). Steatosis is a term used to denote lipid accumulation within hepatocytes. "Mucins are another complex group of molecules known to be important components of the gut barrier with Muc2 deficiency, consistently expressed at lower levels in fiber fed mice in our study, reported to protect mice from diet-induced fatty liver disease and obesity." (PMID 30349136, 2018).
hyperplastic polyp (3 papers, 2010 to 2026). A polyp found mainly in the stomach and colon. "MUC2 expression is maintained in hyperplastic polyps, sessile serrated polyps, and traditional serrated adenomas." (PMID 36900282, 2023). "The fact is that the pattern of expression of MUC1, MUC2, and MUC6 that is reported in the present article for hyperplastic polyps, is identical to what is reported in other studies for normal mucosa." (PMID 20929551, 2010). "MUC2, in contrast, was completely expressed in hyperplastic polyps and tubular adenomas, but was absent in some serrated adenoma, tubulovillous adenoma, and villous adenoma specimens." (PMID 20929551, 2010).
liver cancer (3 papers, 2013 to 2025). An epithelial or non-epithelial malignant neoplasm that arises from the liver. "The expression of MUC2 has been identified in pancreatic and liver cancer." (PMID 24176033, 2013).
lung adenocarcinoma (3 papers, 2022 to 2023). A carcinoma that arises from the lung and is characterized by the presence of malignant glandular epithelial cells. "The immunohistochemical markers of lung adenocarcinoma (CK7, TTF-1, Napsin A) and enteric differentiation (CDX-2, CK20, MUC2, villin) were both expressed in PEAC." (PMID 35172862, 2022).
mucinous ovarian tumors (3 papers, 2015 to 2021). "Expression of several gel-forming mucins has been described for mucinous ovarian tumors such as MUC2, MUC5AC and MUC5B." (PMID 26075384, 2015).
mucositis (3 papers, 2021 to 2022). Mucositis is inflammation and damage of the mucous membranes lining the mouth and other parts of the gastrointestinal (GI) tract. "In line with this, we observed a reduced number of goblet cells and Muc2 protein expression following cSTX, highlighting the role of sympathetic neurons in mucosal immune disorders." (PMID 36010681, 2022). "Although MUC-2 has been shown to have protective capacities, we found that it was upregulated during cisplatin-induced mucositis, especially on day 3, and it reverted to a normal level by day 6 in the probiotic+cisplatin group." (PMID 34568500, 2021). "MUC-2 upregulation may be a counterreaction by the intestine to protect against mucositis, which was also observed in methotrexate-induced damage." (PMID 34568500, 2021).
nasal polyps (3 papers, 2015 to 2020). "Compared with normal nasal mucosa, the expression of MUC3 and MUC6 in nasal polyps is downregulated, the expression of MUC2 and muc8 in nasal polyps is upregulated, the expression of MUC5AC and MUC5B in CRS is upregulated, and the expression of MUC5AC in nasal polyps far exceeded MUC1 and MUC2." (PMID 32812123, 2020). "Studies on the expression of mucin in nasal polyps by using probes to be directed against unique sequence of mucin molecule (discontinuous repeat probes) show that expression level of MUC5AC is four times higher than MUC2 and is twelve times higher than MUC1." (PMID 32812123, 2020). "Among the mucin family members, the expressions of MUC1, MUC2, MUC4, MUC5AC, and MUC5B have been detected in the human nasal polyp and middle ear epithelial cells." (PMID 32054887, 2020). "All studies showed that MUC2 and MUC8 were more strongly expressed in nasal polyps than nasal mucosa." (PMID 32812123, 2020). "Several studies have shown that the major mucins expressed in chronic sinusitis (CS) are MUC2, MUC5AC, and MUC5B and an inverse relationship was found between MUC2 and MUC5AC expression levels and this was strong in the presence of nasal polyps." (PMID 25691903, 2015).
rectal adenocarcinoma (3 papers, 2021 to 2023). "This discovery inspired us to further investigate the expression level and clinical relevance of MUC2 in rectal adenocarcinoma." (PMID 34300195, 2021). "Low MUC2 expression may be further explained by poorly differentiated colorectal and rectal adenocarcinoma or advanced tumor stage in CRC." (PMID 37830585, 2023). "However, our previous study has suggested that MUC2 overexpression is an unfavorable predictive and prognostic factor for rectal adenocarcinoma patients receiving neoadjuvant CCRT." (PMID 36277959, 2022). "MUC2, the major intestinal mucin, has been suggested to carry immunoregulatory signals to favor tumor growth in the large intestine, and our previous study also demonstrated that overexpression of MUC2 is linked to CCRT resistance and poor prognosis in patients with rectal adenocarcinoma." (PMID 36277959, 2022).
rectal tumors (3 papers, 2017 to 2023). "Mice that were genetically deficient in MUC2 spontaneously developed severe intestinal inflammation, which frequently progressed to invasive adenocarcinoma and rectal tumors at a later age63." (PMID 36759578, 2023).
signet ring cell carcinoma (3 papers, 2013 to 2023). A usually aggressive, poorly differentiated invasive adenocarcinoma characterized by the presence of malignant glandular cells in which the nucleus is pressed to one side by the presence of intracytoplasmic mucus. "It is possible that KLF4 and MUC2 could be used as diagnostic markers in signet ring cell carcinoma." (PMID 27277677, 2016).
urachal adenocarcinomas (3 papers, 2013 to 2022). "A comparable distribution was detected for MUC2 and MUC5AC with high positivity rates in urachal adenocarcinomas (100% and 92%) and lower rates in colorectal and primary bladder adenocarcinomas." (PMID 36010242, 2022). "A comparable distribution was detected for MUC2 and MUC5AC with high positivity rates in urachal adenocarcinomas (100% and 92%) and lower rates in colorectal and primary bladder adenocarcinomas, however, with significant overlap." (PMID 29721106, 2018). "Useful biomarkers of urachal adenocarcinomas, like alpha-methylacyl-CoA racemase (AMACR, p504s), CD15 (Leu-M1), carcinoembryonic antigen (CEA), CK34βE12 (high-molecular weight cytokeratin), GATA binding protein 3 (GATA3), mucin 2 (MUC2), and mucin 5AC (MUC5AC), should be taken into consideration." (PMID 36010242, 2022).
villous adenoma (3 papers, 2010 to 2023). An epithelial neoplasm morphologically characterized by the presence of a villous architectural pattern. "The epithelial tissue of the intestinal subtype resembles the villous adenoma of the colon and contains goblet cells, which express the MUC2 protein and the CDX2 transcription factor." (PMID 37575378, 2023). "Colonic villous adenoma-like growth pattern and immunohistochemical profile of MUC2-, MUC5AC- and CDX2-positivities but MUC1- and MUC6-negativities in the present case indicated that the lesion was consistent with the intestinal type IPMN." (PMID 34674710, 2021). "Only 5 cases including 2 serrated adenomas, 1 tubulovillous adenoma, and 2 villous adenomas stained negative for MUC2." (PMID 20929551, 2010). "Only five cases had negative MUC2 staining, of which 2 were serrated adenomas, 1 was tubulovillous adenoma, and 2 were villous adenomas." (PMID 20929551, 2010).
acute pancreatitis (2 papers, 2022). An acute inflammatory process that leads to necrosis of the pancreatic parenchyma. "Previous study in our laboratory showed that dietary supplementation of pectin could enhance intestinal barrier function, increase the expression of Claudin-4 and Muc-2 in the cecum of piglets, and abolish the abnormal expression of ZO-1 and Occludin caused in the acute pancreatitis model." (PMID 36569061, 2022). "For example, MOS reduce intestinal mucosal barrier damage in rats with acute pancreatitis by increasing the expression of claudin-1, ZO-1, and mucin 2 (muc2)." (PMID 35784342, 2022).
amebic colitis (2 papers, 2016 to 2017). "Gut IL-25 and mucus protein Muc2, both shown to provide innate immunity in the mouse model of amebic colitis, were lower in antibiotic pre-treated mice." (PMID 28817707, 2017).
bile duct tumor (2 papers, 2012 to 2014). "However, recent molecular biological studies suggested the correlations of the expression of MUC-1 and MUC-2 mucin antigens with the prognosis of intrahepatic bile duct tumors." (PMID 24727803, 2014).
bronchiectasis (2 papers, 2016). Segmental, irreversible dilation of the bronchial tree resulting in the accumulation of secretions which leads to obstruction. "Recent studies have identified specific profiles of mucins (proteins secreted by airway epithelium and found in sputum), airway disorders such as COPD, and bronchiectasis, with high levels of MUC2 gene found in the latter condition." (PMID 27941638, 2016). "Mucins described in bronchiectasis (MUC2) may reflect bacterial load and P. aeruginosa colonisation and bronchiectasis severity as measured by the BSI (MUC2 and MUC5AC), suggesting a potential future role in incorporating these by-products in characterising phenotypes." (PMID 27941638, 2016).
celiac disease (2 papers, 2006 to 2021). An autoimmune genetic disorder with an unknown pattern of inheritance that primarily affects the digestive tract. "Furthermore, we found that the inflammatory state of the small intestinal mucosa in patients with active celiac disease is associated with ectopic production of MUC2 by enterocytes." (PMID 16755296, 2006).
cervical cancer (2 papers, 2024 to 2025). A primary or metastatic malignant neoplasm involving the cervix. "Whether MUC2 promotes PNI in cervical cancer through selective adhesion and EMT or by generating a mucous barrier to protect cancer cells from recognition by antitumor immune effectors is not yet known." (PMID 39061654, 2024).
co-infection (2 papers, 2019 to 2021). "Furthermore, the occurrence of pulmonary fungal coinfection negatively correlated with MUC2 and MUC20 mRNA expression and specifically in the deceased patients." (PMID 34448730, 2021).
colon polyps (2 papers, 2017 to 2021). "In our study, though we had expected to be able to detect an increase in Muc-2 transcription in Selenof-KO mice, given the observed increase in goblet cell size, no increase in Muc-2 mRNA was detected in scrapes of colons nor in colon polyps." (PMID 34638991, 2021).